MLANA (melan-A)
Diseases named in the same sentence as MLANA in open-access papers (continued):
Sharing a sentence is not in itself a finding about the gene and the disease.
tumor (continued). "The tumor cells were diffusely positive for factor XIIIa and ALK, but were negative for AE1/AE3 keratin, alpha-smooth muscle actin, CD30, CD34, CD68, PU.1, melan A, MITF, and S-100 protein." (PMID 29747676, 2018). "Evaluation of primary tumor expression of NY-ESO-1 and Melan-A tumor was determined by immunohistochemistry (IHC)." (PMID 30400835, 2018). "IHC studies demonstrated tumor expression of NY-ESO-1 and Melan-A in 78% and 81% of the patients, respectively." (PMID 30400835, 2018). "The diagnosis of these rare tumours predominately depends on immunohistochemistry and the characteristic coexpression of melanocytic (HMB45 and/or melan A) and smooth muscle markers (actin and/or desmin)." (PMID 25821471, 2015). "In immunohistochemical study, tumor cells express melanocytic markers (HMB-45, Melan-A) and variably smooth muscle markers (smooth muscle actin, muscle-specific actin) and hormone receptors (estrogen and progesterone receptors)." (PMID 25890370, 2015). "PEComa is a family of rare tumours consisting of perivascular epithelioid cells (PECs) that coexpress melanocytic (HMB45 and/or melan A) and smooth muscle markers (actin and/or desmin)." (PMID 25821471, 2015). "Immunohistochemical analysis revealed that the tumor cells expressed HMB45, Melan-A, SMA, HHF35, Desmin, and pathogenesis-related protein, and were negative for all other markers tested." (PMID 25621681, 2015). "Immunohistochemistry revealed that the tumor cells in all cases were positive for HMB-45 (20/20) and melan-A (9/9)." (PMID 24348838, 2014). "Immunostains were performed in which the viable adrenal cortical tumor cells expressed AE1/3 (weak, diffuse), melan A (strong, diffuse), and inhibin (moderate, diffuse), but were nonreactive for PAX8, CAIX, CD68, and CD163." (PMID 25108298, 2014). "Tumour cells were vimentin, synaptophysin, calretinin, inhibin, CD56 and melan A-positive, consistent with the literature." (PMID 24602387, 2014). "The tumor cells were found to be positive for HMB45 and Melan-A, based on which the lesion was diagnosed as AM." (PMID 23533832, 2013). "The epithelioid tumor cells were diffusely positive for HMB-45, Melan-A, and focally positive for calponin." (PMID 23587410, 2013). "The immunohistochemistry staining showed that the tumor cells were diffusely positive for S-100, CD1a, langerin and CD68, but negative for CD3, CD5, CD20, CD21, CD30, CD38, CD56, CD79a, ALK, HMB-45, Melan-A, pan-cytokeratin and MPO." (PMID 23388086, 2013). "Immunohistochemically, tumor cells were positive for HMB45, Melan A, S100 protein, and only focally for CD138/syndecan-1." (PMID 23133774, 2012). "Lymph node involvement was identified in one of the eleven isolated lymph nodes (isolated tumor cells, showing positivity for S-100 protein, HMB45, and Melan A)." (PMID 23024873, 2012). "Histologically, PEComas are composed by a hybrid tumor cell which is characterized by immunoreactivity for both melanocytic (HMB45 and/or Melan-A) and smooth muscle (α-smooth muscle actin and/or desmin) markers." (PMID 22957287, 2012). "The neoplasm was immunoreactive for Melan-A, MITF, and S-100 protein indicating melanocytic lineage of the tumor cells." (PMID 18638402, 2008). "Immunohistochemical studies showed that the tumor cells were negative for Melan-A, HMB-45, PRAME, cytokeratin, CD34, and Factor XIIIa." (PMID 40636637, 2025). "Immunohistochemical (IHC) staining demonstrated tumor cells positive for Melan-A (MART-1) and SRY-related HMG-box (SOX10) and negative for AE1/3 keratin, a cytokeratin." (PMID 39006602, 2024). "Immunohistochemistry for melan A showed strong diffuse tumour cell positivity, HMB45 was mainly negative with only single cell positivity." (PMID 37415400, 2024). "The recurrent tumour and lymph nodes metastases were completely negative for Melan-A and PRAME, and focally positive for SOX10." (PMID 39001214, 2024).
tumor (continued). "On immunohistochemistry, these tumor cells were diffuse (>90%) strong positive for HMB45 and patchily (20-30%) strong positive for Melan A. These tumor cells were also positive for smooth muscle actin (SMA), which showed stronger positivity in tumor cells, showing a whorling pattern." (PMID 39021472, 2024). "Tumor cells in the 2 cases were positive for vimentin, HMB45, Melan-A, and S-100." (PMID 38335433, 2024). "Melan-A, along with HMB-45, was used for staining melanocytes and melanophages, aiming to identify and quantify the presence of melanin and melanocytic cells in the tumor tissue." (PMID 39399171, 2024). "Immunohistochemical stains showed positivity in tumor cells for S-100, HMB-45, and Melan-A." (PMID 39280438, 2024). "In addition, focal staining for Melan-A, weak chromogranin A staining, partial, patchy desmin staining and weak heterogonous NSE immunoreactivity was detected in the tumor cells." (PMID 35501497, 2023). "Together, these data provide compelling evidence that lymphatic, as opposed to systemic, administration of CBI monotherapy results in more effective anti-tumor responses both with and without Melan-A VLP vaccination." (PMID 35406595, 2022). "The tumor cells were positive for SOX10, S100, Melan-A, and HMB45." (PMID 36289768, 2022). "Immunoperoxidase stains were performed on a Ventana NEXES Automated Immunohistochemistry System (Fuzhou Maixin Biotech Co., Ltd., Fuzhou, China) Vimentint, HMB45 and Melan A were positive in the tumor cells, while CKp, S-100, SOX-10, and CD68 were negative." (PMID 36686734, 2022). "We chose Melan-A/MART-126-35 and NY–ESO-1157-165 antigens to validate our assay, because these are two important tumor antigens exploited in various active and passive tumor immunotherapy strategies." (PMID 36032094, 2022). "Furthermore, immunohistochemistry analysis revealed that tumor cells were positive for S-100 protein, HMB-45, Melan-A, and SOX10." (PMID 33478436, 2021). "We ruled out leiomyomatosis by HMB45 expression in our tumor and also excluded malignant melanoma by negative for Melan-A and S-100 in our tumor." (PMID 34465349, 2021). "The tumor cells were negative for any other melanocytic markers such as S100, Melan A, MITF, SOX10, all myogenic markers (SMA, MSA, desmin, caldesmon) and cytokeratins." (PMID 31309284, 2020). "The immunohistochemical profile showed tumor cells that express Melan-A and smooth muscle actin, while they were negative for pan-cytokeratin, PAX8, CK7, CD117 and CD34." (PMID 33344317, 2020). "On IHC, tumour cells were positive for HMB45, Melan-A, and actin." (PMID 33520482, 2020). "The seven cases with either missing tumour or little/no melan-A labelling, underwent sectioning of the whole tissue block and were re-labelled in the study." (PMID 30060843, 2018). "In repeated biopsy in July 2015 histopathological workup showed a pleomorphic epitheloid tumor with small to medium sized cells expressing vimentin and melan-A while being negative for cytokeratin establishing the diagnosis of PEComa of the liver." (PMID 29463266, 2018). "On immunohistochemistry, the tumor cells expressed vimentin and melan-A, but were negative for cytokeratin." (PMID 29463266, 2018). "Tumour foci, i.e., GFP and melan-A-positive cells, were clearly observed in diaphgram tissue." (PMID 30584259, 2018). "By immunohistochemistry, some tumor cells were weakly positive for epithelial membrane antigen (EMA), but they were negative for cytokeratin, smooth muscle actin (SMA), desmin, S-100, Melan-A, and CD34." (PMID 28471957, 2017). "Analysis revealed that the tumor cells were immunopositive for vimentin, microphthalmia transcription factor, S100, CD1a, CD10, CD63, and folliculin, but immunonegative for cytokeratin, α-smooth muscle actin, HMB45, Melan-A, and PNL-2." (PMID 27871249, 2016).
tumor (continued). "Current case is unique in that the tumor lacked reactivity for melanin-associated antigens HMB-45 and Melan-A, which is similar to some angiomyolipomas from skin, head and neck." (PMID 26754205, 2016). "Immunohistochemical analysis of tumor cells indicated the following: HMB-45(+); vimentin(+); smooth muscle actin (SMA)(+); melan-A(+); CK(−); hepatocyte(−); Arg-1(−); GPC-3(−); CK7(−); CK19(−); CK20(−); S-100(−); CD34 blood vessel endothelium(+); and no exact tumor suppository." (PMID 26698563, 2015). "Furthermore, the sarcomatous component of the tumor was positive for HHF, myogenin, and caldesmon, whereas the epithelial component was diffusely positive for inhibin, melan-A, S-100 protein, NSE and HMB-45." (PMID 25435950, 2015). "Vice versa, proliferation also occurred at the same level in the tumor cells Mark1/Melan A positive as in the negative (Ki-67 image)." (PMID 26378036, 2015). "Immunohistochemistry results in our patient showed diffuse positivity for HMB-45 and S-100 protein and weak patchy cytoplasmic positivity for Melan A. Also tumor cells were negative for EMA and GFAP." (PMID 26294993, 2015). "The tumor thickness was 1.6 mm, and tumor cells were positive for S100, gp100, and Melan-A (data not shown)." (PMID 26083413, 2015). "On immunohistochemistry the tumor cells showed diffuse positivity for human melanin black-45 (HMB-45) antibody and S100 and weak patchy cytoplasmic positivity for antimelanosomal antibody MART-1 (Melan A) which were all suggestive of melanocytic origin." (PMID 26294993, 2015). "The lipid-containing tumor cells were negative for Melan A, a finding that is inconsistent with adrenal cortical neoplasm, although not exclusive." (PMID 25574414, 2014). "Immunohistochemical staining of the tumour showed positive reaction to the tumour cells for Vimentin, S100 protein, and Melan A and negative reaction for muscle actin, smooth muscle actin, desmin, and HMB-45." (PMID 25374957, 2014). "Immunohistochemistry showed the tumour cells to be positive for synaptophysin, vimentin, and melan-A and negative for chromogranin." (PMID 24716005, 2014). "Initial immunohistochemistry studies showed nonreactivity of the tumor for pancytokeratin, epithelial membrane antigen, synaptophysin, chromogranin, Melan-A, and CD10." (PMID 25574414, 2014). "Immunohistochemically, the tumor cells, including signet-ring cells, were diffusely positive for S-100 protein, vimentin and Melan-A, but negative for HMB-45, cytokeratin (AE1/AE3 and CAM5.2), nestin, peripherin, α-internexin and GFAP." (PMID 24348822, 2014). "The tumor lacked reactivity for melanin-associated antigens HMB-45 and Melan-A, and for CD31, pan-cytokeratin (AE1/3) and desmin." (PMID 23628229, 2013). "Based on their high precursor frequencies, it has been argued that Melan-A-specific T-cells are unusual and not representative of other tumor-antigen-specific T-cells." (PMID 22347406, 2012). "Tumor cells were strongly and diffusely positive for HMB45, Melan A, and vimentin." (PMID 23133774, 2012). "The tumor cells were positive immunostaining for HMB-45, Melan-A, and smooth muscle actin." (PMID 22978636, 2012). "On immunohistochemical staining, the tumor cells were positive for HMB45 (DAKO, Carpenteria, CA, USA), S100 (DAKO, Carpenteria, CA), and Melan-A (Novocastra, Newcastle-Upon-Tyne, UK), whereas they were negative for cytokeratin (AE1/AE3) and epithelial membrane antigen." (PMID 23170958, 2012). "In this case the tumor cells expressed HMB45, melan A and smooth muscle actin." (PMID 21846376, 2011). "The cumulative frequency of such Melan-A specific clusters within the CD8+ DP population was only slightly lower than the total frequency of all identified Melan-A specific TCRs, indicating that our approach was able to identify most of the high-frequency tumor-specific clonotypes." (PMID 35377314, 2022).
tumor (continued). "However, on immunohistochemistry, the tumor cells showed immunoreactivity for Melan A and SMA and were negative for PAX-8, Pan-Cytokeratin, Myogenin, CD117, CD34, CK7, PAX-8 and HMB-45." (PMID 33344317, 2020). "In addition, EMA and P63 expression was focal, CK18, CK19, HMB45 and melan-A were negative in the tumor cells." (PMID 26315812, 2015). "Because circulating tumor cells (CTC) presenting in the peripheral blood is a prerequisite step of distant metastases, we examined CTC in the animals at 14th day after HIFU treatment by detecting the mRNA of melanocytic markers melanoma antigen gene (MAGE) and Melan-A by qPCR." (PMID 26485753, 2015). "Thus, if such a tumor does not stain for HMB-45 or Melan-A, a specific diagnosis of EAML cannot be made with certainty." (PMID 23628229, 2013). "Immunohistochemical analysis using the recommended minimum antibody panel (CAIX, TFE3, PAX8, HMB-45 and Melan-A, Cathepsin K, AMACR, CK-7, EMA) could be advised routinely for every case of RCC, regardless of the patient′s age and the microscopic features of the tumor." (PMID 35886994, 2022). "In addition, the infusion of T-cells specific for one single tumor antigen could promote tumor escape by favoring the growth of Melan-A negative tumor cells." (PMID 34120214, 2021). "Moreover, tumor cells were negative for caldesmon, desmin, myogenin, and Melan-A and S-100." (PMID 34465349, 2021). "Immunofluorescence confirmed stable expression of melanocytic marker Melan-A across all groups, indicating that PIEZO1 or DOT1L knockdown did not alter the lineage identity of the tumor cells." (PMID 41533929, 2025). "In our case, the tumor showed positivity for S100 and SOX10 but was negative for common melanocytic markers such as HMB-45, Melan-A, and PRAME." (PMID 40636637, 2025). "The tumor was negative for Epcam, TTF-1, p40, GATA3, CD45, calretinin, Melan-A, HMB-45, CD1a, CD163, and desmin." (PMID 41384184, 2025). "Immunohistochemical staining revealed that the tumor cells were positive for S-100, HMG-45, Melan-A, and SOX10 and negative for AE1/AE3." (PMID 38289480, 2024). "On immunohistochemistry, the tumor cells were positive for S100P and SOX-10 and focally positive for HMB-45 and Melan A. Tumor cells were negative for CK, EMA, SMA, TTF1, PAX8, GATA3 and SALL4." (PMID 38509523, 2024). "No immunoreactivity for CK, S100, CD31, ERG, MDM2, CDK4, Melan A, or HMB45 was detected in the tumor cells." (PMID 38388450, 2024). "The tumor cells were negative for CD34, CD117, DOG-1, smooth muscle actin, desmin, chromogranin A (CgA), synaptophysin, human melanoma black-45, and Melan-A." (PMID 38518040, 2024). "Immunohistochemical staining revealed that the tumor was positive for alpha-smooth muscle actin, but negative for CD34, desmin, keratin 18, S-100 protein, melan A, c-kit, and STAT6." (PMID 38805072, 2024). "Immunohistochemical stains were positive for PAX8, AE1/AE3, E-cadherin, CD10, and vimentin; the tumor was negative for CK7, CD117, racemase, ALK, and HMB45; the tumor showed focal, scattered staining for Melan-A and very weak cytoplasmic staining for CAIX." (PMID 39561576, 2024). "Fortunately, this tumour is often easy to distinguish from its non-melanomatous counterparts on the basis of melanocytic marker expression (i.e., HMB-45, Melan-A) and molecular profiling." (PMID 38672534, 2024). "We observed a high concordance with immune cell-related but not tumor cell-related genes (NGFR, MITF, MLANA, SLC45A2) and correlation with expression of PDCD1LG2 and SUSD3, irrespective of the side of metastasis." (PMID 38386085, 2024). "Immunohistochemically, the tumor was positive for alpha-smooth muscle actin, but negative for CD34, desmin, keratin 18, S-100 protein, melan A, c-kit, and STAT6." (PMID 38805072, 2024).
tumor (continued). "On immunohistochemical staining, tumor cells were positive for cytokeratin AE1/AE3, p63, and beta-catenin (nuclear and cytoplasmic staining) and negative for HMB45, Melan-A, S-100 protein, and androgen receptor." (PMID 36843770, 2023). "IHC studies demonstrated that the tumor cells were patchily positive for CD117, Melan-A and desmin, but negative for DOG1." (PMID 37041531, 2023). "Immunophenotypically, the tumor was positive for Cytokeratins Oscar and 7, GATA3, GCDFP, HER2, and an androgen receptor but negative for CK20, S100, p40, Melan A, CDX2, TTF1, ER, SATB2, DOG1, synaptophysin, and chromogranin." (PMID 37886914, 2023). "The tumour cells revealed focal cytoplasmic expression of calretinin and synaptophysin, and they were negative for S100, HMB45, melan A, and chromogranin." (PMID 36604647, 2023). "Tumor cells are typically positive for α-inhibin, calretinin, SF1, Melan-A, CD56 and CD99, and negative for EMA and occasional expression of other keratin markers." (PMID 37518334, 2023). "Immunohistochemical staining showed positivity for smooth muscle actin, HMB45 and Melan-A in the tumor cells, whereas the adjacent liver tissue was negative for HMB45 and Melan-A." (PMID 36964879, 2023). "In the right ankle tumor, S100 and SOX-10 were diffusely positive in spindle tumor cells, while HMB45 and Melan-A were negative." (PMID 37352079, 2023). "Regarding to immunohistochemistry of PMME, most of the tumor cells were HMB45 positive, Melan A positive, S100 positive, and CK negative, and the number of Ki67 positive cells ranged between 40 and 50%." (PMID 35668195, 2022). "The immunohistochemical study shows a moderate partial positivity of tumor cells of PS100 (patchy) and an absence of expression of tumor cells of CK, P63, CD45, HMB45 and Melan A. Ki67 was expressed by 30% of tumor cells." (PMID 35637541, 2022). "Immunohistochemical features of liver aspiration biopsy tissue are as follows: CK19, CK7, CKp, and MUC5AC were positive in tumor cells, while Hepatocyte, CDX-2, TTF-1, HMB45, Melan-A, S100, and SOX10 were negative." (PMID 36686734, 2022). "Clonotypes matching to Melan-A-specific VDJdb entries were prominently enriched within the CD8+ DP subset (about 1.5% of repertoire), compared to fresh-frozen tumor (FFT) tissue and to the CD8+ non-DP subset." (PMID 35377314, 2022). "Immunohistochemical stains showed the tumor cells to be positive for CD117, CD34 and CD10 and negative for ER, PR, CK7, PAX-8, pan-cytokeratin, EMA, S100, Melan-A, HMB45, SMA and CAIX." (PMID 36312876, 2022). "Few features shared by these tumours and ESC RCC are the polygonal cells with abundant vacuolated cytoplasm and positivity for Melan A. However, the macrocystic areas, lack of papillary pattern, CK20 positivity and negative TFE3 favours ESC RCC." (PMID 34514562, 2022). "In contrast, the tumor cells were nonreactive for SF-1, inhibin alpha, desmin, HHF35, HMB45, Melan A, MITF, c-kit, DOG1, cytokeratin AE1/AE3, h-caldesmon, STAT6, CD68, MDM2, CDK4, c17, DHEAST, 3BHSD, CD31, Factor 8, and ERG." (PMID 34797454, 2021). "Tumor cells were nonreactive for SF-1, inhibin alpha, desmin, HHF35, HMB45, Melan A, MITF, c-kit, DOG1, cytokeratin AE1/AE3, h-caldesmon, STAT6, CD68, MDM2, CDK4, c17, DHEAST, 3BHSD, CD31, Factor 8, and ERG." (PMID 34797454, 2021). "Immunohistochemically, the tumor cells of case No. 1 were positive for AE1/AE3, calretinin, D2-40, focal positive for HBME-1 and negative for HMB45, Melan-A, Desmin, Actin, and S100." (PMID 34248850, 2021). "Immunohistochemically, tumor cells were negative for Arg-1, glypican-3 (GPC3), hepatocyte specific antigen (HSA), and positive for synaptophysin (Syn), α-inhibin, and Melan A. The Ki-67 index was 1 %." (PMID 34218806, 2021). "To examine tumor-selective DAMP induction, we utilized the B16F10 (tumorigenic) and Melan-A (non-tumorigenic) cell lines that were derived from C57BL/6 mice." (PMID 33447347, 2020).